KLF4 (KLF transcription factor 4)
Diseases named in the same sentence as KLF4 in open-access papers (continued):
Sharing a sentence is not in itself a finding about the gene and the disease.
thymoma (1 paper, 2021). A neoplasm arising from the epithelial cells of the thymus. "By screening the DEGs that had a significant impact on the prognosis of thymoma, we identified LIPE, MYH6, ACTG2, KLF4, SULT4A1, and TF as key genes." (PMID 34104648, 2021). "This study identified key genes related to the prognosis of thymoma, including LIPE, MYH6, ACTG2, KLF4, SULT4A1, and TF." (PMID 34104648, 2021). "LIPE, MYH6, ACTG2, KLF4, SULT4A1, and TF were the key genes affecting the prognosis of thymoma." (PMID 34104648, 2021). "ACTG2, KLF4, SULT4A1, and TF were all involved in the occurrence or development of cancer, but their biological significance in thymoma was not clear." (PMID 34104648, 2021).
tongue cancer (1 paper, 2016). A malignant neoplasm affecting the tongue. "Here, we examined whether introduction of defined reprogramming factors (Oct4, shp53, Sox2, Klf4, l-Myc and Lin28) into HSC2 tongue cancer cells could transform the HSC2 into HSC2 with CSCs properties." (PMID 27464948, 2016). "In this study, we demonstrated that the introduction of defined reprogramming factors (Oct4, shp53, Sox2, Klf4, l-Myc and Lin28) could generate cells with CSC-like properties from a tongue cancer cell line, HSC2." (PMID 27464948, 2016).
vascular malformation (1 paper, 2016). A non-neoplastic disorder that is the result of defects of vascular morphogenesis. "iCCM1/KLF4 mice showed a macroscopic reduction in the number, size, and extension of the CCM vascular malformations in the cerebellum." (PMID 26612856, 2016). "In conclusion, our data indicate that KLF4 is required for the development and progression of CCM1 vascular malformations." (PMID 26612856, 2016).
vascular tumors (1 paper, 2015). "IHC staining for the stem cell reprogramming factors Oct4, Nanog, Myc, Klf4, and Sox2 was performed in the vascular tumor samples as well as the two control tissue sets." (PMID 26412983, 2015). "Thus, in this study we used immunohistochemical analysis to examine the expression of the stem cell reprogramming factors Oct4, Sox2, Nanog, Myc, and Klf4 in 71 diverse benign and malignant vascular tumors." (PMID 26412983, 2015). "Semi-quantitative evaluation of our immunohistochemical staining revealed that protein expression of Oct4, Nanog, Myc, and Sox2, but not Klf4, was significantly increased in benign, borderline, and malignant vascular tumors relative to non-diseased vascular tissue controls." (PMID 26412983, 2015).
tumor (735 papers, 2007 to 2026). "Conversely, while often associated with M2 polarization or tumor‐promoting effects, increased KLF4 expression can, in certain contexts, promote M1 polarization." (PMID 41532367, 2026). "Overall, the top four checkpoint genes associated with KLF4 and correlated with a tumor inhibitory effect in several tumors were C10orf54, CD274, IL10, and TGFB1." (PMID 40299916, 2025). "KLF4 is a transcription factor closely associated with tumor stem cell characteristics and is involved in cell proliferation, differentiation, and self-renewal." (PMID 41393242, 2025). "NF2 mutations occur in all grades and AKT1 E17K and KLF4 K409Q often co-occur with TRAF7 mutations predominantly in grade 1 tumours." (PMID 40420192, 2025). "For instance, KLF4 is often associated with tumor suppression, while KLF5 has been linked to promoting tumor growth in breast cancer." (PMID 40860800, 2025). "Meanwhile, the top three genes that are least correlated with KLF4 and associated with a tumor inhibitory effect in several tumors were BTLA, IDO1, and LAG3." (PMID 40299916, 2025). "KLF4 is frequently linked to cancer stem cells (CSCs), which possess the ability to self-renew and differentiate into multiple tumor cell types." (PMID 39995670, 2025). "Through enhancer activation and self‐reinforcing loop, Nrf2 and KLF4 co‐opt gene networks linked to epithelial‐to‐mesenchymal transition and tumor growth." (PMID 40755294, 2025). "KLF4 also regulates the differentiation of monocytes into macrophages and tumor-associated macrophages during tissue migration." (PMID 40589762, 2025). "microRNA-206 can inhibit the induced expression of CCL2 in tumor-associated macrophages and cytotoxic T lymphocytes by regulating the Kruppel-like factor 4 (Klf4) transcription factor." (PMID 41341593, 2025). "In our exploration of the core genes CCND2 and KLF4, we identified associations between their expression and the development of specific tumor types." (PMID 40487928, 2025). "The present findings will aid in understanding the role of KLF4 in tumor biology and its association with immune responses." (PMID 40299916, 2025). "Despite being related to Klf4, which has known tumor-suppressive properties, Nanog has been linked to the promotion of tumor growth in breast cancer as well as chemoresistance and regenerative capacity in prostate cancer." (PMID 38247819, 2024). "KLF4 SUMOylation-deficient macrophages promote the expression of M1 macrophage-associated genes in tumor cells and have strong anti-tumor activity." (PMID 38280996, 2024). "The dual oncogenic and tumor suppressor role of KLF4 emerges clearly in the association with chromatin and its structural properties." (PMID 39135777, 2024). "During the tumor metastasis, KLF4 is further downregulated, whereas downregulation of KLF4 is associated with poor prognosis in PDA." (PMID 37031197, 2023). "Regarding the Yamanaka factors, there is concern that if Klf4 and c-Myc, which are involved in carcinogenesis, are accidentally inserted into genomic DNA, there is a risk of disease onset and tumor formation." (PMID 38535481, 2023). "Among the Yamanaka factors, Klf4 and c-Myc are oncogenes, and there is a risk of tumor development if these are integrated into genomic DNA." (PMID 38535481, 2023). "KLF4 had the potential to serve as a biomarker for identifying patients at high risk of tumor progression and recurrence." (PMID 36936440, 2023). "KLF4 regulates HBB transcription in circulating tumor cells, and constitutively active mutations in NRF2 have been reported in various carcinomas, including RCC." (PMID 37239002, 2023).
tumor (continued). "Whole exome sequencing of non-invasive cyst-forming neoplasm called intraductal papillary mucinous neoplasms (IPMNs) identified hotspot mutations in zinc finger domains of KLF4 gene in more than half of IPMNs." (PMID 37239940, 2023). "Conversely, the suppression of KLF4 directly decreased CSC-associated tumor metastasis from the breast to the brain." (PMID 37853437, 2023). "Further studies have revealed that the KLF4 K409Q mutation exhibits enhanced hypoxic signaling and is involved in the adaptation of tumor cells to the anaerobic environment." (PMID 37031197, 2023). "KLF4 encodes a transcription factor that acted as a tumor suppressor which inhibited cell cycle, promoted apoptosis and differentiation, and suppressed metastasis." (PMID 36092919, 2022). "Downregulation of miRNA-7 leads to overexpression of KLF4, causing tumor progression and an enhanced inflammatory response in the tumor environment." (PMID 35159070, 2022). "KLF4 is believed to act as a tumor suppressor, and its low expression is negatively associated with the overall survival rate in gastric cancer patients." (PMID 36077352, 2022). "Klf4 has also been shown to function as a tumor suppressor, with heterozygous loss of function enhancing tumor progression in APCmin mice." (PMID 35359925, 2022). "This is in concordance with our results where high mutational burden in KLF4 leads to low tumor purity and hence greater tumor infiltration of immune cells, specifically macrophages." (PMID 34440860, 2021). "KLF4 is often downregulated in tumor specimens and associated with poor survival in cancer patients." (PMID 32793396, 2020). "Transcription factors involved in embryonic stem cell (ESC) and induced pluripotent stem cell (iPSC) signaling, such as SOX2, OCT4, MYC, and KLF4, have been linked to tumor progression in various cancers." (PMID 32427884, 2020). "Another analyzed transcription factor, KLF4, has been reported to be associated with both oncogenesis and tumor suppression." (PMID 32733958, 2020). "KLF4 has been shown to play a tumor suppressor role during CRC tumorigenesis - its loss accelerates development and progression of cancer." (PMID 32566755, 2019). "Compared with control cells, the loss of KLF4 decreased tumour growth and increased cell apoptosis; however, the phenotypes were reversed by NUCB2 overexpression." (PMID 30055641, 2018). "The integration of exogenous genes encoding transcription factors (OCT4, SOX2, C-MYC, and KLF4) can be detected in iPSCs, raising concern about the risk of mutagenesis and tumor formation." (PMID 30460090, 2018). "While Klf4 expression was associated with the tumor size (T classification) (P=0.043), lymph node invasion (N classification) (P=0.007), distant metastasis (M classification) (P=0.027), and clinical stage (P=0.023) of 94 NPC patients." (PMID 29212199, 2017). "The stemness related genes SOX2, Klf4, Nanog, and Oct4 are expressed in CSCs and are associated with tumor progression." (PMID 28536422, 2017). "Kruppel like factor 4 (KLF4), a transcription factor associated with carcinogenesis and tumor progression, plays an important role in various malignancies." (PMID 29254226, 2017). "The transcription factors of embryonic stem cells, such as Oct4, Sox2, Nanog, Bmi1, and Klf4, are known to be associated with stemness, epithelial–mesenchymal transition and aggressive tumor behavior." (PMID 28422735, 2017). "Klf6 has previously been studied as a tumor suppressor in prostate, ovary, and liver, and Klf4, Klf5, and Klf6 are also implicated as regulators of viability." (PMID 27213272, 2016). "Klf6 has been characterized as a tumor suppressor in prostate, ovary, liver, and gut, and Klf4, Klf5, and Klf6 are also implicated as regulators of viability." (PMID 27213272, 2016). "Numerous studies report a loss of KLF4(FL) expression in tumors, suggesting that KLF4(FL) prevents tumor formation." (PMID 27323810, 2016).
tumor (continued). "As activation of metastasis is one key hallmark of tumor cells, we next investigated the effect of KLF4 on the process." (PMID 27105535, 2016). "KLF4 has been extensively studied in the context of tumors and current data suggest that it can either act as tissue-specific tumor-inhibiting or -promoting gene with the underlying mechanism remaining unclear." (PMID 27323810, 2016). "In MDA-MB-435s, we found that silencing CD44 caused a decrease in KLF4 expression, which is required for the maintenance of the stem cell-like features of tumor initiating cells." (PMID 25605020, 2015). "We identified a significant association between the KLF4 level in both tumor and normal tissue and survival." (PMID 25060774, 2014). "In contrast, KLF4 is regulated post-transcriptionally by miR-2909, and suppression of its expression resulted in loss of KLF4 tumor suppressor activity in pediatric B-ALL." (PMID 25037230, 2014). "Previous work showed that the four factor-derived (Oct3/4, Sox2, Klf4, and c-Myc) iPSCs can cause tumor formation on reactivation of c-Myc." (PMID 24979372, 2014). "The transcription factor Krüppel-like factor 4 (KLF4) has been implicated in human cancers as a tumor suppressor or oncogene, although its role depends greatly on the cellular context." (PMID 25137052, 2014). "KLF4 is another example of a TF with strong growth suppressive and pro-differentiation activities, that is nevertheless associated to tumor promoting functions in specific contexts." (PMID 21072181, 2010). "Other tumor types have also been variously associated with increased or decreased Klf4 expression and function." (PMID 20442780, 2010). "Importantly, nuclear KLF-4 expression remained independently associated with adverse overall survival after adjustment for tumor stage, lymph node status, molecular subtype, and other molecular markers (adjusted HR 4.09, 95% CI 1.93-8.67, p < 0.001)." (PMID 41898441, 2026). "Mutations in the 3′ untranslated region (UTR) and the zinc‐finger domain of the KLF4 gene lead to the loss of its tumor‐suppressing function, which may be a significant factor causing the progression of T‐ALL." (PMID 41532367, 2026). "However, in certain cancers, KLF4 demonstrates oncogenic properties, likely associated with tumor stem cell differentiation." (PMID 39995670, 2025). "In line with our scRNA-seq data showing enrichment of pathways that promote tumor outgrowth in the liver and lungs, these results imply that the KLF4+ and RUNX1+ cell states associated with liver and lung metastases are selected during expansion at the respective metastatic site." (PMID 40999053, 2025). "While current studies associate full-length KLF4 with cancer stemness and tumor immune evasion, it remains unknown whether alternative isoforms such as KLF4α or KLF4a modulate these processes differently." (PMID 40552304, 2025). "Interestingly, in many tumors, KLF4 expression is often reduced or lost, which is associated with poor tumor differentiation." (PMID 40299916, 2025). "These gaps are significant because different KLF4 isoforms may underlie its paradoxical roles as both tumor suppressor and oncogene, as well as its dual influence on inflammatory and anti-inflammatory myeloid phenotypes." (PMID 40552304, 2025). "In diverse tumor types, KLF4 expression is closely associated with macrophage polarization." (PMID 39995670, 2025). "Previous studies have associated ABCG2 and KLF4 with tumor stemness, suggesting that these genes may serve as representative markers and potentially reflect the disparity in tumor stemness between cell types." (PMID 39389944, 2024). "Furthermore, KLF4 has been implicated in inflammation and tumorigenesis and has been identified as a tumor suppressor in HCC." (PMID 39000273, 2024). "On the other hand, increased expression of MMP9, KLF4, and TGFβ induced by p40 monomer could imply a proclivity towards lung remodeling and a tumor-associated macrophage (TAM) phenotype." (PMID 38435456, 2024).
tumor (continued). "However, a few reports also suggested that KLF4 was associated with the stability of tumor stem cells." (PMID 37031197, 2023). "KLF4 deficiency is also associated with tumor development by EMT." (PMID 37031197, 2023). "Therefore, the association of KLF4 with survival seems to be tumor type-specific, and future studies are needed to decipher the interplay between KLF4 and EMT/MET states as a prognostic marker of clinical outcomes in a cancer-specific manner." (PMID 34680284, 2021). "Finally, in vivo tumor xenograft experiments were performed with nude mice to elucidate the effects associated with HOXA10-mediated HDAC1 regulation of DNMT1/KLF4 on the tumorigenic ability of LAD." (PMID 33596966, 2021). "The dysregulation of KLF4 may cause or amplify the tumor-promoting results of the Warburg effect and should be investigated as a potential therapeutic target." (PMID 33917010, 2021). "Likewise, Klf4 has been found to act as a tumor suppressor in gastrointestinal cancer where it is associated with growth arrest through inhibition of G1/S cell cycle progression." (PMID 34195082, 2021). "High KLF4 levels in tumor tissues are associated with both better overall survival rate and recurrence-free survival rate, while low KLF4 expression may mean a poor prognosis for HCC patients." (PMID 33266506, 2020). "Moreover, KLF4 has been linked to tumor metastasis through the regulation of EMT in several forms of human cancers." (PMID 32937756, 2020). "Indeed, KLF4 is often regarded as an inhibitor of cell proliferation and as a tumor suppressor, as it is associated with both GSK3β and AKT signaling pathways." (PMID 32937756, 2020). "However, in the tumor section where KLF4 loss was observed, we noticed increased levels of SNAI2 in the nuclei of the epithelial cells that were defined by positive staining for PanCK." (PMID 32566755, 2019). "In in vitro models, drug resistance induced by elevated HOTAIR expression may be caused by the promotion of tumor sphere cell growth and activation of tumor stem cell biomarkers such as Nanog, Oct3/4, Sox2, c-Myc, β-catenin, and Klf4." (PMID 31072041, 2019). "Expression of KLF4 has been associated with both tumor promotion and suppression." (PMID 30952833, 2019). "Since CSCs are tumorigenic (tumor-forming), and hypothesized to cause relapse and metastasis by giving rise to new tumors, the functions of Klf4 in NPC CSCs may also contribute to the tumorigenesis and metastasis of NPC cells in our study." (PMID 29212199, 2017). "In addition, KLF4 has been linked to tumor metastasis through regulation of the epithelial mesenchymal transition (EMT) in several forms of human cancers." (PMID 26075898, 2015). "In OSCC tissues, KLF4 expression was associated with tumor grade and stage." (PMID 26517087, 2015). "We speculate that the elevated expression of c-Myc and Klf4 was one of the causes of tumor formation." (PMID 26023799, 2015). "In OSCC tissues, KLF4 expression was associated with tumor classification and tumor size." (PMID 26517087, 2015). "However, there are conflicting reports regarding KLF4 expression in tumor cells and its association with overall survival in HCC." (PMID 24897024, 2014). "Moreover, high Klf4 expression levels were associated with aggressive tumor behaviors in terms of vascular invasion (P=0.02) and poor tumor differentiation (P=0.03)." (PMID 23599755, 2013). "KLF4 was identified as a tumor suppressor with loss of expression in a series of cancers." (PMID 22937066, 2012). "Future studies should explore the molecular mechanisms underlying these contrasting effects of KLF4, particularly focusing on how its function may switch between tumor suppressor and oncogene depending on factors such as the activation of the PI3K/AKT, Wnt/β-catenin, or TGF-β pathways." (PMID 40299916, 2025).